ADAM17 (ADAM metallopeptidase domain 17)
Diseases named in the same sentence as ADAM17 in open-access papers (continued):
Sharing a sentence is not in itself a finding about the gene and the disease.
cancer (continued). "ADAM17 is better characterised than iRhoms with respect to cancer, although until recently it too has not been the subject of the intense focus commensurate with its regulatory importance." (PMID 35971826, 2022). "Given that ADAM17 is depleted in the cancer cell population, we speculated that the cancer cells are the source of HB-EGF, and we confirmed that reexpression of ADAM17 in Adam17–/– 4T1 cells rescued the secretion of HB-EGF." (PMID 35998057, 2022). "ADAM28 may play a key role in cancer cell proliferation and metastasis, whereas ADAM17 is a target of tumorigenesis, but the role of ADAM15 in cancer biology remains to be elucidated." (PMID 35565436, 2022). "Moreover, we demonstrate that ADAM17/HB-EGF signaling regulates the education of protumorigenic macrophages, the expression and secretion of chemokines, as well as macrophage-induced cancer cell dissemination." (PMID 35998057, 2022). "In addition, the results uncovered that the expression of ADAM17 was positively correlated with an immunostimulator (IL6R) and immunoinhibitors (CD274, KDR, TGFBR1) in most cancer types." (PMID 35720350, 2022). "Although consistently indicating that ADAM17 plays a relevant role in cancer progression and outcome, these reports did not yield a consensus value that supported the use of ADAM17 as a biomarker." (PMID 36140519, 2022). "Next, we tested whether the cancer cell lines secrete CXCL1 and whether the secretion is influenced by ADAM17." (PMID 35998057, 2022). "Mechanistically, we demonstrated that ADAM17-dependent shedding of EGFR ligands directed protumorigenic macrophage education, leading to increased secretion of CXCLs and consequent macrophage-induced cancer cell invasion." (PMID 35998057, 2022). "On a similar note, our group recently reported that the interaction between cellular integrin α5β1 and ADAM17 on EVs participates in the binding and uptake of CRC EVs by recipient PMCs and cancer cells, which is relevant in the process of peritoneal dissemination." (PMID 35628559, 2022). "These preliminary results provedthe efficacy of bifunctional inhibitors in cancer cells overexpressingADAM8, but further studies will be needed to improve the selectivityof compound 2 for ADAM8 over ADAM17 and to ultimatelydefine its mechanism of action at a molecular level." (PMID 35111280, 2021). "Furthermore, in a promising way, the relationship between ADAM17 activation, inflammation and EMT seems to be an unexpected feature in the progression of organ fibrotic diseases and cancer." (PMID 34362154, 2021). "In addition, Soto-Gamez and colleagues have developed an innovative therapeutic approach to target the function of ADAM17 in EGFR activation and cancer progression." (PMID 33579029, 2021). "In support of this notion, ADAM17 is overactivated or overexpressed in numerous human chronic inflammatory diseases, and it is noted that EMT represents a convergence point between inflammation and the progression of degenerative fibrotic diseases and cancer." (PMID 34362154, 2021). "ADAM17 may be involved in Notch and Wnt signaling pathway, and TGF-β/Smad pathway, which may promote the development of cancer." (PMID 32610677, 2020). "We demonstrated that the impairment of shedding does not alter the ability of CA IX to bind ADAM17, internalise, form oligomers and regulate pH, but induces cancer-promoting changes in extracellular proteome." (PMID 32210366, 2020). "In cancer cells, APP was demonstrated to regulate ADAM17 gene expression." (PMID 29988083, 2020). "One specific example could be to use the oncolytic virus as a gene therapy vector to deliver small interfering RNA (siRNA) within the cancer cell, knocking down ADAM10 and ADAM17 expression, and thus prevent NKG2DL shedding." (PMID 33352921, 2020).
cancer (continued). "C-X3-C motif chemokine ligand 1 (CX3CL1)/fractalkine is a chemokine released after cleavage by two metalloproteases, ADAM metallopeptidase domain 10 (ADAM10) and ADAM metallopeptidase domain 17 (ADAM17), involved in inflammation and angiogenesis in the cancer microenvironment." (PMID 30845779, 2019). "Collectively, our discovery of a druggable ADAM17‐sIL‐6R axis in KRAS mutant LAC represents an attractive new strategy for the development of therapies for LAC and potentially other oncogenic KRAS‐addicted cancers." (PMID 30833304, 2019). "Since ADAM17 mediates the ectodomain shedding of various pro-tumourigenic cytokines, growth factors and surface receptors, it is of no surprise that ADAM17 has attracted attention as a potential driver of cancer." (PMID 31438559, 2019). "Collectively, these findings identify ADAM17 as a druggable target for oncogenic KRAS‐driven LAC and provide the rationale to employ ADAM17‐based therapeutic strategies for targeting KRAS mutant cancers." (PMID 30833304, 2019). "It will now be of great interest to further evaluate whether ADAM17‐mediated sIL‐6R shedding and ERK activation are restricted to mutant KRAS LAC or are also a driver event in other mutant KRAS cancers (e.g., colorectal and pancreatic)." (PMID 30833304, 2019). "D1(A12) does not cross-react with murine ADAM17, thereby limiting its usefulness and development as a cancer therapeutic agent." (PMID 29230082, 2017). "Since the membrane-bound form of GPC1 appears to regulate adhesion, proliferation, and migration of carcinoma cells, downregulation of its shedding with an ADAM17 inhibitor would not likely be advantageous for treating many types of cancer." (PMID 29230082, 2017). "ADAM17 and MMP14 are particularly well known for their ability to promote cancer progression." (PMID 26308720, 2015). "ADAMs shown to play a role in cancer include ADAM9, ADAM10, ADAM12, ADAM15 and ADAM17." (PMID 21906355, 2011). "Although the regulation of EGF-like factor expression in cancer cell lines has been reported, the mechanisms of EGF-like factor and TACE/ADAM17 expression in cumulus cells cultured with FSH and/or LH have remained unclear during in vitro maturation of porcine COCs." (PMID 20034375, 2009). "ADAM17, also known as TNF-alpha–converting enzyme (TACE), plays a pivotal role in inflammation, but has also emerged as a key regulator of several physiological and pathophysiological processes, such as cell proliferation, immune cell activation, cell death, inflammation, and cancer." (PMID 38139236, 2023). "In LUAD, KRAS mutation contributes to the phosphorylation of ADAM17 threonine via p38 MAPK, thereby driving ADAM17 to selectively promote its substrate IL-6R shedding and subsequent ERK1/2 MAPK-IL-6-mediated trans-signal transduction, leading to malignant progression of the cancer." (PMID 36466812, 2022). "To identify the factor(s) responsible for ADAM17-dependent macrophage education, we performed an unbiased quantitative tandem mass tag–mass spectrometry–based (TMT-MS–based) proteomics analysis of the secretome from macrophages cocultured with WT or Adam17–/– 4T1 cancer cells." (PMID 35998057, 2022). "Furthermore, CXCL1 secretion in the cancer cells was not affected by Adam17 knockout, indicating that CXCL1 originates from the macrophages in our cocultures." (PMID 35998057, 2022). "In addition, inhibition of ADAM17 expression in NK cells, for instance using CRISPR/Cas9 or siRNA, could be used to prevent shedding of CD16 on NK cells used for cancer immunotherapy." (PMID 34070311, 2021). "Therefore, 1,25(OH)2D inhibition of TACE (Tumor necrosis factor Alpha Converting Enzyme, also known as ADAM17), a metalloproteinase overexpressed in several cancer types, may further explain its antiproliferative effects." (PMID 32560347, 2020).
cancer (continued). "Inhibition of cleavage of TLR2 by ADAM17 may or may not be helpful for either cancer or inflammatory processes as soluble TLR2 ectodomain can negatively regulate TLR2 activation by behaving as a decoy receptor." (PMID 29230082, 2017). "However, Incyte is currently using their dual ADAM17 and ADAM10 inhibitors in the clinic to enhance the properties of rituximab, likely because it acts as a stimulator of the patient's immune response to cancer." (PMID 29230082, 2017). "Given the known role of the EGFR in pathologies such as cancer and auto-immune diseases, the physiological and translational significance of our findings is that they provide new insights into how the processing and functional activation of EGFR-ligands by ADAM17 may be regulated." (PMID 36361585, 2022). "However, promoter methylation in other cancer types may not be the only mechanism regulating ADAM17 overexpression." (PMID 36558177, 2022). "ADAM17 proteolytically cleaves and activates several EGFR ligands such as epiregulin, transforming growth factor alpha (TGF-alpha), amphiregulin (AREG) and heparin-binding EGF-like growth factor (HB-EGF) and may thus contribute to cancer progression through EGFR activation." (PMID 36140519, 2022). "Therefore, early-stage cancers are totally absent in this study and we could have missed the population where ADAM17 could be a strong biomarker." (PMID 36140519, 2022). "However, it is not clear whether targeted ADAM17 therapies are effective for cancer treatment and targeted ADAM17 therapies are still in the exploratory stage." (PMID 32610677, 2020). "Thus, the pharmacological modulation of ADAM17 may represent a means to target the non-cell autonomous effects of cellular senescence, which may contribute to different diseases, including cancer." (PMID 26260680, 2015). "β integrins expressed on the surface of cells lacking ALCAM expression can mediate the binding and uptake of cancer-derived EVs lacking ALCAM through their interactions with specific EV ligands, such as the ADAM17 or fibronectin." (PMID 35628559, 2022). "Interestingly, ADAM17 might also represent a master-switch during several fibrotic pathologies and has a central role in the regulation of the epithelial-to-mesenchymal transition (EMT), a critical cellular process in cancer metastasis and pathological fibrosis." (PMID 34362154, 2021). "ADAM17 exhibited negative correlations with ACE2 (normal: R −0.187; cancers: R −0.044) and FURIN (normal: R −0.281; cancers: R −0.079)." (PMID 33796097, 2021). "The non-cancerous bile ducts showed negative or weak staining for ADAM-10, ADAM-17, and ADAM-28, whereas most cancer cells showed strong staining for these three proteins." (PMID 29776401, 2018). "Similarly, the expression levels of various other ADAM17 processed substrates and pEGFR were not elevated in LAC versus cancer‐free lung lysates (Fig EV4C)." (PMID 30833304, 2019).
infection (84 papers, 2007 to 2025). The state of being infected such as from the introduction of a foreign agent such as serum, vaccine, antigenic substance or organism. "T cell-specific deficiency in ADAM17 led to increased effector CD8+ T cell generation in response to pathogenic infection." (PMID 38918390, 2024). "Reduced ADAM10 and ADAM17 surface expression upon infection and inflammatory stimulation, respectively, are linked to their release in exosomes, which was reduced by Ca2+ chelation." (PMID 39497138, 2024). "Given the importance of effector CD8+ T cells in protecting against pathogenic infection, we first examined ADAM17 deficiency in CD8+ T cells in an acute infection model." (PMID 38918390, 2024). "Here, loss of ADAM17 led to an early increase of neutrophil recruitment to the peritoneal cavity 2 h after infection, whereas it turned into a decreased recruitment compared to WT mice after 24 h." (PMID 37849760, 2023). "As EGFR family member activation is implicated in infection with viruses from various families including DNA and RNA viruses and ADAM17 was reported as a papilloma virus entry factor, we asked how specific the observed ADAM10 effect was." (PMID 37967063, 2023). "Infection was reported to be associated with increased levels of a disintegrin and metalloprotease domain 17 (ADAM17)." (PMID 36952548, 2023). "In conclusion, cells with functional ADAM17, or cells in the neighborhood of such cells, are susceptible for infection mediated by the cleavage of membrane-bound growth factor precursors." (PMID 31107240, 2019). "It has been reported that the skin of two children with a loss-of-function mutation in ADAM17 was prone to infection with S. aureus." (PMID 26808616, 2016). "In contrast, infection with carriage isolates lead to prolonged activation of NF-κB that was associated with a transient activation of JNK increased TACE/ADAM17-mediated shedding of TNFR1 and protection against apoptosis." (PMID 22144896, 2011). "It is known that preventing TNF-α activity can increase host susceptibility to infection, and thus it will be important to determine the role of leukocyte ADAM17 in pulmonary defense against bacterial infection." (PMID 21603616, 2011). "Surprisingly, compared to mice transferred with WT CD8+ T cells, those with ADAM17 KO CD8+ T cells had significantly reduced bacterial colonies on agar plates in both spleen and liver 4 days and 7 days after infection, suggesting an enhanced effector function of ADAM17 deficient CD8+ T cells." (PMID 38918390, 2024). "Thus, infection with P. aeruginosa leads to an increase in cell-associated ADAM17 expression, maturation and shedding activity." (PMID 35892600, 2022). "Taken together, high serum sACE2 levels were hypothesized to be associated with increased ADAM17 activity, reduced mACE2 levels, a reduced anti-inflammatory response, and an increased risk of infection-related hospitalization in patients on maintenance HD." (PMID 35155493, 2022). "However, a recent study on HEK293T cells revealed that both TMPRSS2 and metalloproteases, particularly ADAM17, individually or co-operatively, promote activation of S2′ segment of S protein and syncytia formation in infection by SARS-CoV-2 and its emerging variants of concern." (PMID 36851081, 2023). "We also observed that ADAM10 and ADAM17 levels were elevated shortly after infection but decreased below control levels by the final time point (day 120)." (PMID 40725601, 2025). "An interesting possibility is that ADAM10 and ADAM17 direct trafficking of CXCR6+ T cells to different tissues as a consequence of their increased activity upon infection of parenchymal cells by particular pathogens." (PMID 40043065, 2025). "The results showed that the ratio of ADAM17 KO to WT CD8+ T cells was remarkably increased in the peripheral blood lymphocytes (PBL) after infection compared to an equal number transferred." (PMID 38918390, 2024).
infection (continued). "ADAM17, a cell surface sheddase, is an essential factor for infection of bovine cells with several pestiviruses." (PMID 39459898, 2024). "Cells were lysed at 24, 48 and 72 h post-infection (hpi), and the amounts of mature and immature ADAM17 were relatively quantified by Western blot analysis compared with mock-treated cells employing an antibody interacting with the ADAM17 cytoplasmic domain." (PMID 39459898, 2024). "In line with this idea, our findings indicate that in healthy close contacts and LTB, ADAM17 acts principally by shedding TNF to maintain concentrations sufficient to keep infection control below a pathological threshold." (PMID 38881671, 2024). "We observed different changes in the cellular levels of mature and immature ADAM17, as well as changes in their ratios, depending on the pestivirus species used for infection." (PMID 39459898, 2024). "This species-specific effect correlates with the susceptibility of persistently pestivirus-infected cells to infection with a cytopathic BVDV-1 (cpBVDV-1), potentially implementing the direct role of ADAM17 in superinfection exclusion of certain pestiviruses." (PMID 39459898, 2024). "On the other hand, our data suggest a little effect of ADAM17 on TNFRs during LTB or resistance to infection status since the levels of these receptors were lower in healthy close contacts of ATB cases." (PMID 38881671, 2024). "Future studies on these zoonotic RNA viruses will clarify a potential role of ADAM10 and ADAM17 in infection." (PMID 37967063, 2023). "Their expression level reached normal levels at the 48 h and 72h time points, except for ACE-2 and ADAM17, which were upregulated even in the late phase of infection (72 h)." (PMID 36851710, 2023). "A protein mutant lacking ADAM17 intracellular domain completely reestablished the infection in ADAM17-KO cells, suggesting that the protein serves as an attachment factor during CSFV entry and not as a virus internalization receptor." (PMID 38041163, 2023). "Recently, Jocher and co-workers have identified the function of ADAM10 and ADAM17 during SARS-CoV-2 infection using pharmacological and genetic approaches, showing that ADAM17 is required during the early stages of infection." (PMID 37763019, 2023). "Evidence for ADAM17-mediated infection of SARS-CoV-2 in human lung cells suggests that ADAM17 triggers SARS-CoV-2 invasion by cleaving the S protein of the virus." (PMID 36558177, 2022). "ADAM17 has functions in regulating many cell surface receptors and molecules which influence the immune response to infection." (PMID 35215094, 2022). "One step up in the cascade, we investigated the role of ADAM17 on THP-1 cell adhesion during infection with P. aeruginosa." (PMID 35892600, 2022). "In contrast to ADAM10, both single knock‐outs of ADAM17 reduced infection by 40–50%, and this rate was further reduced by the addition of BB94." (PMID 35527514, 2022). "L-selectin and ADAM17 have clear fundamental roles in controlling the migration of leukocytes during infection." (PMID 35215094, 2022). "As proteolytic cleavage of ACE2 by ADAM17 and TMPRSS2 affects susceptibility to infection, it is possible that recent trypsin treatment also impact ACE2 cleavage on target cells." (PMID 36289285, 2022). "In general, the increase in ADAM17 activity upon ExoA stimulation was weaker than observed upon infection with P. aeruginosa, but comparable to PMA control stimulation." (PMID 35892600, 2022). "Those patients can survive but suffer from recurrent infections or tylosis with oesophageal cancer, highlighting the importance of the iRhom2/ADAM17 axis in immunity, host defence and cancer." (PMID 32825187, 2020). "More specifically, a low CD9 expression level supports infection as well as ADAM17 sheddase activity and the ADAM17-mediated ERK signalling pathway." (PMID 32385608, 2020).